HOTTIP (HOXA distal transcript antisense RNA)
Diseases named in the same sentence as HOTTIP in open-access papers (continued):
Sharing a sentence is not in itself a finding about the gene and the disease.
ovarian carcinoma (continued). "In ovarian cancer, the levels of lncRNA GAS5 was downregulated, while lncRNA HOTTIP was upregulated, indicating that lncRNA GAS5 and HOTTIP may be the futuristic diagnostic biomarkers." (PMID 36059539, 2022). "Contrarily, ovarian cancer has progressed due to inhibition of pyroptosis induced by lncRNA HOTTIP." (PMID 36618967, 2022). "According to one study, HOTTIP may affect ovarian cancer development and progression by modulating neutrophil activity." (PMID 36612180, 2022). "In ovarian cancer tissues and cell lines, lncRNA HOTTIP is upregulated, the knockdown of which could lead to pyroptosis, hampering the progression of OVCA." (PMID 35198448, 2022). "Finally, ZEB2 was identified as the gene target of miR-205, thus completing the elucidation of HOTTIP-miR-205-ZEB2 as the novel axis which is functionally involved in the determination of cisplatin resistance in ovarian cancer cells." (PMID 34322490, 2021). "In this study, we hypothesized a possible role of lncRNA HOTTIP (HOXA transcript at the distal tip) in the cisplatin resistance of ovarian cancer cells." (PMID 34322490, 2021). "HOTTIP has been implicated in cisplatin resistance of pancreatic cancer cells which would suggest its similar role in other cancers, such as ovarian cancer as well, but to-date there has been no report on the subject." (PMID 34322490, 2021). "To check if our hypothesis for the possible role of HOTTIP in cisplatin resistance of ovarian cancer cells was correct, we measured the levels of HOTTIP in a paired cell line model that comprised of cisplatin sensitive A2780 cells and their cisplatin resistance derivatives (A2780-CR)." (PMID 34322490, 2021). "The silencing of HOTTIP inhibited ovarian cancer cell rapid growth and invasion as well as migration in vitro, whereas the greater expression of HOTTIP increased invasion in ovarian carcinoma cells, suggesting that HOTTIP could be one of the markers for unsuitable prognosis in OC cases." (PMID 37854681, 2023). "In conclusion, lncRNA HOTTIP modulates the miR-615-3p/SMARCE1 pathway, thereby enhancing ovarian cancer growth and metastasis." (PMID 37854681, 2023). "HOTTIP increased the expression of PD-L1 in neutrophils, which increased the IL6 levels and promoted the immunological evasion of ovarian carcinoma." (PMID 37854681, 2023). "A recent study suggested that silencing of lncRNA HOTTIP results in the inhibition of cell proliferation and NLRP1 inflammasome-mediated pyroptosis in ovarian cancer." (PMID 35712671, 2022). "Contrary to SATB2-AS1, lncRNA HOTTIP could decrease Th1 infiltration through upregulating the expression of the cytomembrane molecule PD-L1 by enhancing STAT-3 activity, thereby accelerating the immune escape of ovarian cancer." (PMID 37637063, 2023). "For this study, we focused on the lncRNA HOTTIP because of its immense potential as a biomarker but without any prior exploration in cisplatin resistance of ovarian cancer even though there is an indication for it role in cisplatin resistance of other human cancers." (PMID 34322490, 2021).
osteosarcoma (21 papers, 2017 to 2024). A usually aggressive malignant bone-forming mesenchymal neoplasm, predominantly affecting adolescents and young adults. "In osteosarcoma, HOTTIP overexpression was also found to be associated with poor response to chemotherapy by activating the Wnt/β-catenin pathway." (PMID 32457911, 2020). "In vitro experiments revealed that enhanced HOTTIP expression markedly promoted MG-63 osteosarcoma cells into S phase, while HOTTIP downregulation significantly arrested the cell cycle in G1 phase." (PMID 34130697, 2021). "Meanwhile, researchers found that lncRNA HOTTIP can decoy miR-27a-3p to promote G protein subunit gamma 12 (GNG12)-mediated metastasis in osteosarcoma." (PMID 35071016, 2021). "This corroborates a number of previous studies that found HOTTIP to promote chemoresistance in numerous cancer entities, including osteosarcoma in which the regulation of Wnt/β-catenin by HOTTIP was also described." (PMID 32756406, 2020). "When it comes to osteosarcoma, overexpression of lncRNA HOTTIP increases chemoresistance of osteosarcoma cell by activating the Wnt/β-catenin pathway." (PMID 29928484, 2018). "HOXA Distal Transcript Antisense RNA (HOTTIP) was detected at heightened concentrations in human osteosarcoma tissue." (PMID 28353666, 2017). "Osteosarcoma patients with elevated HOTTIP expression had poorer overall survival than those with low HOTTIP expression." (PMID 28353666, 2017). "HOTTIP plays a pivotal role in osteosarcoma cell initiation and chemoresistance via activating Wnt/β-catenin signaling pathway." (PMID 27806342, 2017). "Decreasing HOTTIP induced cell cycle arrest in G1 phase through inhibiting the Wnt/β-catenin pathway, thus reversing drug resistance in osteosarcoma." (PMID 28978183, 2017). "Multivariate Cox proportional hazards regression analysis revealed HOTTIP expression to be an independent prognostic factor of overall survival in osteosarcoma patients." (PMID 28353666, 2017). "Recently, an investigation showed that HOTTIP could regulate the cisplatin sensitivity in osteosarcoma." (PMID 34130697, 2021). "The lncRNA HOTTIP (human homeobox A transcript) in osteosarcoma (OS) catalyzes LATS2 promoter methylation, inhibits LATS2 expression, activates YAP, initiates downstream target gene expression, and maintains OS cell viability, proliferation, migration, and invasion." (PMID 35071016, 2021). "Thus, HOTTIP was proposed to sensitize osteosarcoma cells in cisplatin-based chemotherapy via Wnt pathway, uncovering a novel network in osteosarcoma treatment." (PMID 34130697, 2021). "A similar study demonstrated that lncRNA HOTTIP was over-expressed in osteosarcoma cells and may facilitate migration, invasion, and EMT in vitro by forming a positive feedback loop with MYC." (PMID 33081056, 2020). "MYC over-expression may promote osteosarcoma cell migration and invasion in vitro, which may be related to the pro-metastatic role of HOTTIP in osteosarcoma cells." (PMID 33081056, 2020). "HOTTIP knockdown suppressed osteosarcoma cell proliferation, migration, and invasion in vitro." (PMID 32566641, 2020). "The overexpression of HOTTIP was correlated with chemoresistance in human osteosarcoma cell lines." (PMID 28353666, 2017). "Importantly, HOTTIP was the first lncRNA documented to regulate Wnt expression in osteosarcoma." (PMID 34130697, 2021). "Targeting HOTTIP may therefore prove to be beneficial for osteosarcoma treatment." (PMID 34691083, 2021). "Besides, up-regulating HOTTIP accelerates osteosarcoma cell proliferation." (PMID 33585440, 2020). "Li et al71 also indicated that up‐regulated HOTTIP could initiate tumorigenesis and induce drug resistance via activating the Wnt pathway, which suggested that HOTTIP may be a potential therapeutic target in osteosarcoma." (PMID 29392884, 2018). "For example, nine lncRNAs (91H, FGFR3-AS1, BCAR4, TUG1, UCA1, HIF2PUT, HOTTIP, HULC, and MALAT-1) are up-regulated in osteosarcoma, which is considered oncogenic for osteosarcoma." (PMID 31850493, 2020).
osteosarcoma (continued). "Till now, the prognostic roles of multi-types of lncRNAs have been investigated in osteosarcoma as well, consisting of HULC, HOTTIP, MEG3, TUSC7, TUG1, 91H, and OMRUL, etc." (PMID 28415638, 2017). "The altered lncRNA expression profile possessed a total of 9 individuals, yet 7 of them (TUG1, 91H, HULC, BANCR, FGFR3-AS1, HOTTIP, and OMRUL) were overexpressed in osteosarcoma tissues/plasma, and 2 (MEG3 and TUSC7) were down-regulated." (PMID 28415638, 2017). "Although these results suggest that HOTTIP may regulate GNG12 through ceRNA and is involved in osteosarcoma progress, further experimental studies are needed to confirm these conclusions." (PMID 34691083, 2021). "Nevertheless, HOTTIP, miR-27a-3p, and GNG12 are all potential therapeutic targets for osteosarcoma." (PMID 34691083, 2021). "Among the altered lncRNA profiles, 7 lncRNAs involved TUG1, 91H, HULC, BANCR, FGFR3-AS1, HOTTIP and OMRUL, were notably increased in patients with osteosarcoma and strongly correlated to worse clinical outcomes, indicating that such lncRNAs may play oncogenic roles in maintaining tumor progression." (PMID 28415638, 2017).
glioma (20 papers, 2015 to 2025). A benign or malignant brain and spinal cord tumor that arises from glial cells (astrocytes, oligodendrocytes, ependymal cells). "In glioma patients, high HOTTIP expression was linked to poor overall survival, according to Kaplan–Meier survival analysis (p = 0.032)." (PMID 40004471, 2025). "Thus, HOTTIP holds great promise as a novel diagnostic and prognostic marker and therapeutic target for glioma." (PMID 27733185, 2016). "However, HOTTIP levels in gliomas tissues and the underlying role and mechanism of HOTTIP in gliomas remain unknown." (PMID 27733185, 2016). "though prior research highlights their roles in glioma tumorigenesis and potential as biomarkers, particularly in the context of HOTTIP." (PMID 40004468, 2025). "They reported that HOTTIP was elevated in glioma cells that had both acquired and natural resistance to chemotherapy, with a critical mechanistic function for EMT and miR-10b." (PMID 40616679, 2025). "HOTTIP was significantly upregulated in glioma cell lines treated with hypoxia; additionally, hypoxic conditions promoted mesenchymal marker vimentin as well as aggressive behaviour in examined cell lines." (PMID 37239035, 2023). "Mechanistically, HOTTIP blocked the expression of mir-101 to upregulate the expression of ZEB1 in glioma cells, thus promoting EMT and metastasis." (PMID 37239035, 2023). "This meant that the relationship between HOTTIP and miR-10b is valid in all glioma cells that turn resistant against TMZ." (PMID 35402278, 2022). "Elucidation of a miRNA, downstream of HOTTIP in glioma cells, particularly those resistant to therapy, was another important goal of this study and for this we screened thirty potential miRNAs, based on available literature." (PMID 35402278, 2022). "Based on the results that we presented in this study, it is reasonable to conclude that lncRNA HOTTIP confers resistance against TMZ in glioma cells." (PMID 35402278, 2022). "There is a lot of published literature on involvement of these miRNAs in therapy resistance in different cancers, however, we are the first to provide a mechanism of miR-10b mediated EMT in the HOTTIP-regulated TMZ resistance of glioma cells." (PMID 35402278, 2022). "Our results thus present a case for HOTTIP in native as well as acquired resistance of glioma cells against chemotherapy, with a key mechanistic role of EMT and the miR-10b." (PMID 35402278, 2022). "The majority of available evidence shows that the expression of the lncRNA HOTTIP is mainly downregulated in gliomas." (PMID 34316694, 2021). "The results indicate that overexpression of HOTTIP inhibits the growth of glioma cell lines (u87-mg, u118-mg, U251, and A172), so high levels of HOTTIP reduce glioma cell growth." (PMID 32883200, 2020). "HOTTIP expression was markedly decreased in glioma tissues compared with normal tissues, and the expression of HOTTIP in glioma cell lines was significantly decreased compared with expression in immortalized human astrocytes." (PMID 27733185, 2016). "The data described in this study indicate that HOTTIP is an interesting candidate for further functional studies in glioma and demonstrate the potential application of HOTTIP in glioma therapy." (PMID 27733185, 2016). "This, we demonstrated that BRE was post-transcriptionally regulated by HOTTIP in U87-MG glioma cells." (PMID 27733185, 2016). "Statistically, average HOTTIP expression levels were decreased in glioma tissue samples; particularly, the expression of HOTTIP was significantly decreased in high-grade glioma tissue samples." (PMID 27733185, 2016). "HOTTIP expression in glioma cell lines was significantly decreased compared with that in immortalized human astrocytes." (PMID 27733185, 2016). "The data described in this study indicate that HOTTIP is an interesting candidate for further functional studies in glioma and suggest the potential application of HOTTIP in glioma therapy." (PMID 27733185, 2016).
glioma (continued). "This is the first report to demonstrate the functional significance of HOTTIP expression in glioma, and our findings indicate that HOTTIP functions as a tumour suppressor gene in glioma." (PMID 27733185, 2016). "In this study, we show that HOTTIP expression is down-regulated in glioma tissues and glioma cell lines." (PMID 27733185, 2016). "To identify the role of HOTTIP in glioma, we analysed the expression of HOTTIP in 85 human glioma tissue samples and 15 human normal brain tissue samples using quantitative real-time RT-PCR." (PMID 27733185, 2016). "Are HOTTIP-mediated inhibition of glioma cell proliferation and induction of glioma cell apoptosis related to BRE?" (PMID 27733185, 2016). "We also evaluated the expression of HOTTIP in four glioma cell lines (U251, U87, A172, and U118) and immortalized human astrocytes using qRT-PCR." (PMID 27733185, 2016). "Therefore, more research is required to determine the significance of HOTTIP and miR-10b as targets for glioma therapy." (PMID 40616679, 2025). "Additionally, miR-10b silencing upon the HOTTIP overexpression promoted TMZ chemosensitivity in all examined glioma cell lines." (PMID 37239035, 2023). "We also further experimentally confirmed our hypothesis for the involvement of miR-10b in HOTTIP mediated TMZ resistance of glioma cells." (PMID 35402278, 2022). "Thus, our results established a role of HOTTIP in inducing several parameters in glioma cells that can impact resistance against therapy." (PMID 35402278, 2022). "Thus, HOTTIP as well as miR-10b are critical targets for glioma therapy, and need to be tested further." (PMID 35402278, 2022). "In glioma, there is one published report on the role of HOTTIP in EMT." (PMID 35402278, 2022). "However, A recent study has found that HOTTIP also possesses antitumor properties, which shows that HOTTIP inhibits glioma proliferation by promoting apoptosis by downregulating the BRE gene." (PMID 35210436, 2022). "Thus, here we checked m6A modifications of previously reported glioma associated lncRNAs: MALAT1, NEAT1, XIST1, TUG1, CRNDE, LINC00461, and HOTTIP." (PMID 35361860, 2022). "HOTTIP was aberrantly down-regulated in glioma, and over-expression of HOTTIP inhibited the growth of glioma in vitro and in vivo by regulation of BRE (brain and reproductive) gene expression, besides, HOTTIP promotes hypoxia-induced EMT of malignant glioma by regulating the miR-101/ZEB1 axis." (PMID 30376874, 2018). "The expression of the lncRNA HOTTIP is mainly down-regulated in glioma." (PMID 30583549, 2018). "Hence, we deduced that over-expression of HOTTIP inhibited glioma cell proliferation and promoted glioma cell apoptosis by down-regulating the expression of BRE." (PMID 27733185, 2016). "To further investigate the role of HOTTIP in glioma progression, we used flow cytometry." (PMID 27733185, 2016). "HOTTIP was aberrantly down-regulated in glioma tissues and glioma cell lines (U87-MG, U118-MG, U251 and A172), and over-expression of HOTTIP inhibited the growth of glioma cell lines in vitro and in vivo." (PMID 27733185, 2016). "We further demonstrated that over-expression of HOTTIP decreased the expression of BRE mRNA and BRE protein in the U87-MG and U118-MG glioma cell lines, as assessed by qRT-PCR and Western blot, respectively, and we confirmed that HOTTIP directly inhibited BRE expression, as assessed by RIP." (PMID 27733185, 2016).